SLCO1B3 (solute carrier organic anion transporter family member 1B3)
Diseases named in the same sentence as SLCO1B3 in open-access papers (continued):
Sharing a sentence is not in itself a finding about the gene and the disease.
cancer (65 papers, 2010 to 2026). A tumor composed of atypical neoplastic, often pleomorphic cells that invade other tissues. "Cancer-type OATP1B3 (Ct-OATP1B3) is a newly identified splice variant of solute carrier organic anion transporter family member 1B3 (SLCO1B3)." (PMID 35717493, 2022). "Later studies found that a variant of the liver-type SLCO1B3 mRNA (Lt-SLCO1B3) is expressed in human cancer tissues and cell lines." (PMID 34526411, 2021). "Recent studies have also linked SLCO1B3 with resistance to anti-cancer treatments." (PMID 40165896, 2025). "In addition, the mRNA expression of SLCO1B3 (OATP1B3) in cancer cells as well as in normal tissue was shown to be associated with the DNA methylation status around the transcriptional start site." (PMID 36839686, 2023). "These conflicting reports may be due to a number of factors including; BC type, sample type and detection technique or could be due to expression of a cancer-specific variant gene, e.g. SLCO1B3 v1 found in colon and pancreatic cancers." (PMID 32388639, 2020). "In this study, the ARGs signature consisted of four genes (RAMP1, FOXL1, SLCO1B3, and F2RL2) that have previously been documented to be closely linked with cancer." (PMID 40165896, 2025). "Using UALCAN, we analyzed the SLCO1B3 transcript expression level in the normal liver tissues from healthy individuals and cancer liver tissues in HCC patients from different subgroups classified by gender, N stage, disease stage, and disease grade." (PMID 40734706, 2025). "SLCO1B3 contributes to the development of several cancers and regulates tumor sensitivity to chemotherapy." (PMID 38507521, 2024). "Our laboratory has previously demonstrated enrichment of the cancer-type solute carrier organic anion transporter family 1B3 (ct-SLCO1B3) and the ATP Binding Cassette Subfamily Member C (ABCC3) in castration-resistant cell lines (CRPC)." (PMID 38213719, 2024). "Cancer-type SLCO1B3 transcripts were specifically detected in RDEB-cSCC cell lines (n = 7) and isolated from extracellular vesicles, both in vitro and in the serum of tumor-bearing mice." (PMID 38769503, 2024). "Due to alternative splicing, the SLCO1B3 gene encodes two protein variants; the hepatic uptake transporter liver-type OATP1B3 (Lt-OATP1B3) and the cancer-type OATP1B3 (Ct-OATP1B3) expressed in several cancerous tissues." (PMID 36986600, 2023). "SLCO1B3 expresses in different types of cancer cells and is responsible for the uptake of several hormones." (PMID 37858151, 2023). "MT1M, SLCO1B3, SPINK1, and AKR1B10 were cancer-related genes that were associated with different human diseases, especially in HCC." (PMID 36246599, 2022). "In this respect, cancer-type solute carrier organic anion transporting polypeptide 1B3 (Ct-SLCO1B3) has been shown to be a highly cancer-specific transcript in several different cancers." (PMID 35008999, 2022). "Cancer-type organic anion transporting polypeptide 1B3 (Ct-OATP1B3), a newly discovered splice variant of solute carrier organic anion transporter family member 1B3 (SLCO1B3), has been reported to be overexpressed in several types of cancer." (PMID 35717493, 2022). "The expression of SLCO1B3 and its functional change have been detected in a variety of malignant tumors." (PMID 33436824, 2021). "Next-generation sequencing revealed that SLCO1B3 knockdown affected the expression of several genes involved in cancer invasion, metastasis, and DNA repair." (PMID 34526411, 2021). "This cancer-type SLCO1B3 mRNA (Ct-SLCO1B3) has a different transcription initiation site from the Lt-SLCO1B3, and its translated product (Ct-OATP1B3) mainly localized in the cytoplasm of cancer cells." (PMID 34526411, 2021). "In contrast to their widespread overexpression in some cancers, several groups have shown that expression of both SLCO1B3 and SLCO1B1 is decreased in hepatocellular carcinoma at both the mRNA and protein levels." (PMID 32388639, 2020).
cancer (continued). "While it has been presumed that the SLCO1B3 gene detected in cancers was identical to that seen in the healthy liver, a cancer-specific variant, OATP1B3 V1, is now known to arise due to alternative splicing." (PMID 32388639, 2020). "Solute carrier organic anion transporter family, member 1B3 (SLCO1B3) is expressed in a number of hormone-dependent cancer types including sub-types of CRC." (PMID 26894861, 2016). "Taken together, we have analyzed the differential regulation of Lt- and Ct-SLCO1B3 gene expression in cancer-derived cell lines of different origin and could demonstrate cell type-specific regulation." (PMID 36986600, 2023). "Importantly, our group has previously shown that Ct-SLCO1B3 constitutes a cancer-specific target gene in RDEB-SCC." (PMID 35008999, 2022). "Thus, our results demonstrate the applicability of RTM44-mediated targeting of the cancer gene Ct-SLCO1B3 in a different malignancy." (PMID 35008999, 2022). "We identified two poorly characterized, human-specific transporters (SLCO1A2, SLCO1B3) whose loss of function protects against doxorubicin-cardiotoxicity, but does not affect cell death in cancer cells." (PMID 34230586, 2021). "However, with unique markers such as C1r and C1s, the progression of cSCC can be monitored, and Cancer type-SLCO1B3 transcripts may be used to detect RDEB-cSCC metastases." (PMID 38769503, 2024). "Furthermore, correlations between the expression of these transcription factors and the expression of Ct-SLCO1B3 could help to further investigate the impact of Ct-OATP1B3 on the clinical outcome of cancer patients." (PMID 36986600, 2023). "Thus, Ct-SLCO1B3 may serve as a defense mechanism in cancer cells to sustain tumor growth under hypoxic conditions." (PMID 34526411, 2021). "Interestingly, the splice variant of SLCO1B3 known as cancer-type OATP1B3 is highly expressed in GAC, whereas it is absent in the healthy stomach." (PMID 32751679, 2020). "Although our analysis did not discriminate between lt-SLCO1B3 and the cancer-type variant, it is most likely that ct-SLCO1B3 might be the prominent isoform in the tumors investigated." (PMID 30131693, 2018). "Using UALCAN, we further examined protein expression levels of SLCO1B1, SLCO1B3, and SLCO2B1 in normal liver tissues from healthy individuals and cancer liver tissues from HCC patients, based on data from the CPTAC dataset." (PMID 40734706, 2025). "Interestingly, gene SLCO1B3, which encodes uptake transporter OATP1B3 was 15.6-fold up-regulated only in cancer tissue of these patients without LVI and this may increase uptake of E1-S and thus also its intracellular concentration." (PMID 33917029, 2021). "However, we did not observe significant co-expression of SLCO1B7 with SLCO1B3 in our cohort, but co-expression with the cancer-specific variant might be possible." (PMID 30131693, 2018). "OATP1B3 (SLCO1B3), normally and specifically expressed in liver, has been found in different cancer tissues." (PMID 26056583, 2014). "We completed a study examining SLCO1B3, SLCO1B1 and SLCO2B1 mRNA expression in 381 primary, independent patient samples representing 21 cancers and normal tissues." (PMID 21625523, 2011). "Using UALCAN, gene transcript expression levels of SLCO1B1, SLCO1B3, and SLCO2B1 were shown to be significantly downregulated in the clinic-pathological characteristics (gender, nodal metastasis status, cancer stages and tumor grade) in HCC patients compared to normal counterparts." (PMID 40734706, 2025). "Furthermore, we were able to detect Ct-SLCO1B3 mRNA levels in late stages of head and neck SCC tissue arising in the normal population, suggesting that this could be an additional cancer that could be targeted by RTM44." (PMID 35008999, 2022).
cancer (continued). "Therefore, future studies are warranted to elucidate the expression pattern of SLCO1B7 with ct-SLCO1B3 in cancer to elucidate whether a functional LST-3TM12 protein in HGSOC exits and to gain information to its relation to drug resistance and cancer progression." (PMID 30131693, 2018).
tumor (61 papers, 2011 to 2026). "OATP1B3 (encoded by SLCO1B3) is highly expressed in some aggressive tumours and confers apoptosis resistance, acting as a key regulator in mediating drug resistance." (PMID 39550701, 2024). "Correlation analysis revealed that high tumorous SLCO1B3 was associated with advanced disease stage, tumor invasion, lymph node metastasis, poor tumor differentiation, and low overall survival." (PMID 34526411, 2021). "SLCO1B3 expression was associated with tumours of high histological grade, adverse survival and increased risk of early recurrence." (PMID 32388639, 2020). "At the single-cell level, the expression of DUSP2 and SLCO1B3 was significantly different between tumor tissue and normal tissue." (PMID 38507521, 2024). "This reflects the hepatocellular background of both cell lines and the expression of the Lt-OATP1B3 protein in mostly healthy tissues, but contrasts with the expression of the Ct-SLCO1B3 mRNA in tumorous tissues." (PMID 36986600, 2023). "Accordingly, the level of Ct-SLCO1B3 expression should be determined for each tumor entity and patient, and these data should be used to select those patients most likely to benefit from this treatment strategy." (PMID 35008999, 2022). "An in vivo study showed that Ct-SLCO1B3 transcriptions were only present in EVs isolated from RDEB tumor-bearing mice who received RDEB-SCC2 cell xenografts." (PMID 36291882, 2022). "We found that high SLCO1B3 expression in human CRC tissues was associated with advanced disease, tumor invasion, lymph node metastasis, and poor patient survival." (PMID 34526411, 2021). "We have shown that abiraterone, one of the most commonly prescribed drugs for CRPC, induces a significant upregulation of SLCO1B3 transcripts in 22Rv1 and VCaP cells and in mice bearing 22Rv1 tumor xenografts." (PMID 34031488, 2021). "This study found that high SLCO1B3 expression in human CRC tissues is associated with advanced disease stage, tumor invasion, lymph node metastasis, poor tumor differentiation, and poor OS." (PMID 34526411, 2021). "In ER+ tumours, SLCO1B3 expression signified a good prognosis, and as oestrogen is a substrate for this transporters, it has been implicated in hormone-dependent growth mechanisms." (PMID 32388639, 2020). "To study the underlying mechanism of impaired docetaxel tumour accumulation, we examined the impact of testosterone on docetaxel uptake by the influx drug transporter OATP1B3 (encoded by SLCO1B3)." (PMID 32989230, 2020). "In a recent study we have reported that the levels of SLCO1B1 and SLCO1B3 mRNA are lower in HB tissue than in the adjacent non-tumor liver tissue." (PMID 30909445, 2019). "OATP transporters have been involved in the uptake of vincristine and the expression of both SLCO1B1 and SLCO1B3 have been found lower in HB than in adjacent non-tumor tissue." (PMID 30909445, 2019). "GPR56, LY6G6D/F and SLCO1B3 protein expression was significantly correlated with the proximal tumor location and with expression of mismatch repair genes." (PMID 26894861, 2016). "Abiraterone‐induced SLCO1B3 up‐regulation provides a prerequisite for greater uptake of nodularin‐R by 22Rv1 cells, which may contribute to the synergistic anti‐tumour effects of both drugs." (PMID 39550701, 2024). "We designed RTM44 to trans-splice to the tumor-specific target pre-mRNA of Ct-SLCO1B3." (PMID 35008999, 2022). "SLCO1B3 was detectable in 2 of 4 patient tumours, and when present it was detected at high levels." (PMID 34225768, 2021). "However, in normal breast tissue samples and tumours, SLCO1B3 expression was detectable in two studies using both microarray analysis and qPCR." (PMID 32388639, 2020). "Herein, we reported a new circRNA, which originates from exon 9 to exon 15 of the SLCO1B3 gene (named circSLCO1B3), orchestrated ICC progression by promoting tumor proliferation, metastasis and immune evasion." (PMID 38641828, 2024).
tumor (continued). "Apart from SKP2, ITGB4, CDKN3, TFGP1, SLCO1B3, CDX2 and KIF18A, the remaining model genes showed significant correlations with stem cell score, immune score and tumour microenvironment." (PMID 39656479, 2024). "Expression frequencies were determined for SLCO1B3, SLCO1B1, and SLCO2B1, and the percent of normal or tumor tissues expressing SLCOs are reported." (PMID 21625523, 2011). "Interestingly, we detected tcGT events with a known tumor suppressor gene RNF43 and two oncogenes ETS2 and SLCO1B3 supporting the extensive contribution of TEs during tumorigenesis." (PMID 38272908, 2024). "As some tumor tissues had similar SLCO expression frequencies as normal tissues, we also ascertained if the magnitude of SLCO expression was different for SLCO1B1, SLCO1B3, and SLCO2B1." (PMID 21625523, 2011). "Further analysis of histopathological data indicated that SLCO1B3 might be important for uptake of E1-S in tumours without lymphovascular invasion where it was 15.6-fold up-regulated as compared to adjacent control tissue." (PMID 33917029, 2021). "Nevertheless, in the seven-gene model, the remaining four genes—PLK1, TRAF2, SLCO1B3, and ZEB2—though not consistently expressed in tumor epithelial cells, also exhibit either oncogenic or tumor-suppressive functions." (PMID 41187171, 2025).
adenocarcinoma (2 papers, 2016 to 2017). A common cancer characterized by the presence of malignant glandular cells. "Three of the markers: GPR56, LY6G6D/F and SLCO1B3 had significantly higher expression in proximal adenocarcinomas and were positively correlated with mismatch repair protein expression, i.e. PMS2 and MSH6 with all three, and PMS1 with LY6G6D/F." (PMID 26894861, 2016).
SLCO1B3 also shares sentences with these, for which no sentence is quoted: liver cancer (9 papers); non-small cell lung carcinoma (3); acute lymphoblastic leukemia (2); adenoma (2); cholangiocarcinoma (2); Cirrhosis (2); colon adenocarcinoma (2); COVID-19 (2); gastric cancer (2); gastric tumor (2); glioblastoma (2); hepatitis C (2); myopathy (2); thyroid cancer (2); tuberculosis (2); bladder cancer (1); blood cancer (1); brain tumours (1); Burkitt lymphoma (1); Dubin-Johnson syndrome (1); end stage renal disease (1); familial intrahepatic cholestasis (1); fatty liver disease (1); fibrosarcoma (1); gastritis (1); Gilbert syndrome (1); Jaundice (1); leukemia (1); liver failure (1); metastatic prostate carcinoma (1).
A further 16 diseases each share a sentence with SLCO1B3 in 1 paper.